SPINK1 (serine peptidase inhibitor Kazal type 1)
Diseases named in the same sentence as SPINK1 in open-access papers (continued):
Sharing a sentence is not in itself a finding about the gene and the disease.
tumor (continued). "Lastly, using in vivo models such as chicken embryo chorioallantoic membrane assay (CAM) and murine xenograft models, we show that silencing SPINK1 expression affected intravasation of cancer cells, tumor growth and distant metastases." (PMID 26258891, 2015). "Recent studies of SPINK1 in different cancers have focused on tumor tissue staining of SPINK1, and on the potential functional effects of SPINK1 on tumor growth and progression." (PMID 26437224, 2015). "SPINK1 has subsequently been found to be secreted into the blood and urine by a variety of other tumor types." (PMID 26437224, 2015). "To investigate whether the association of SPINK1 with poor patient survival is driven by strong association within one or more specific tumor subtypes, we next analyzed association of SPINK1 staining with overall survival in patient subsets defined by tumor morphology." (PMID 26437224, 2015). "In this cell line, high SPINK1 expression increased cell proliferation and invasion both in vitro and in tumour xenografts." (PMID 23527199, 2013). "SPINK1-positive tumour cells were present in 79% of HCC overall, but were present in 91% of HH-HCC, 91% of ALD-HCC, 75% of HCV-HCC, 88% of HBV-HCC and 85% of cryptogenic-HCC." (PMID 23527199, 2013). "SPINK1 expression in background non-tumour liver was localized to the luminal surface of large bile ducts in all cases which is compatible with the physiological function of SPINK1." (PMID 23527199, 2013). "Both approaches may resensitize tumor cells, representing promising targets for SPINK1 in combinatorial chemotherapy." (PMID 40904507, 2025). "In addition to hepatic differentiation markers, the expression of tumor-associated markers (GPC3, SPP1, SPINK1, and KPNA2) was examined across all cell models." (PMID 40862732, 2025). "Elevated SPINK1 expression correlates with poor prognosis and tumor grade." (PMID 40872585, 2025). "In SPINK1-knockdown xenograft tumor models, a reduction in tumor weight exceeding 50% was observed." (PMID 40904507, 2025). "Inhibiting SPINK1 reduces tumor growth and enhances chemosensitivity." (PMID 40872585, 2025). "Four distinct subsets of tumor cells were identified based on gene signatures such as the epithelial–mesenchymal transition, cell cycle and hypoxia, the interferon response, and high levels of serine peptidase inhibitor Kazal type 1 (SPINK1)." (PMID 39410050, 2024). "However, SFRP2, SPINK1, CXCL11, CXCL13, and CXCL10 exhibited gene copy loss in certain tumor populations." (PMID 38577604, 2024). "Notably, SPINK1 also assumes critical functions in cancer pathogenesis, and has been identified as dysregulated in many tumor types, including HCC." (PMID 38540686, 2024). "Here we show SPINK1 to strongly associate with CD133 + HCC, and tumor dedifferentiation." (PMID 38030644, 2023). "Knockdown of SPINK1 also diminished tumorigenicity in vivo, with a marked decrease in tumor incidence and tumor-initiating frequency, concomitant with an increased tumor latency and tumor-free survival, than HCC cells expressing the non-target scrambled control." (PMID 38030644, 2023). "However, there have been limited studies on the role of SPINK1 in the context of tumor plasticity and cancer stemness." (PMID 38030644, 2023). "Finally, we performed vivo experiments and confirmed that knockdown of SPINK1 distinctly suppressed tumor growth in HCC." (PMID 38093163, 2023). "In summary, SPINK1-induced tumor lineage plasticity may represent the Achilles’ heel for surviving chemotherapy-enriched tumor-initiating/propagating cells in HCC." (PMID 38030644, 2023). "In addition to SPINK1-mediate tumor plasticity, other signaling pathways such as the NOTCH pathway have been reported to be activated in CD133 + HCC cells after 5-FU treatment." (PMID 38030644, 2023).
tumor (continued). "Yet, we show here that 5-FU or cisplatin chemotherapy enrich for CD133/Prom1, suggesting that while CD133 may be proliferative, they may also harbor other mechanisms (e.g., SPINK1-mediated tumor plasticity) that enable them to resist standard chemotherapy." (PMID 38030644, 2023). "SPINK1 immunostaining was characterized by heterogeneity of the cytoplasmic expression of tumor cells; of the 72 prostate ADK cases analyzed, 61 cases (84.72%) were classified as having a SPINK1 negative status and 11 cases (15.27%) had a SPINK1 positive status." (PMID 37894380, 2023). "We firstly mined the cDNA expression data of the 1,884 human HCC samples, which showed that the SPINK1 gene was significantly overexpressed in stage I–IV tumor samples relative to para-tumor specimens and presented better discrimination and calibration capabilities for HCC detection than AFP." (PMID 35924241, 2022). "We performed a comprehensive pathological review of over 300 RPs from a prospectively collected multi-institutional cohort and mapped and graded each tumor focus based on H&E examination and molecular classifiers (ERG rearrangement, SPINK1 overexpression, PTEN deletion, and SPOP mutation)." (PMID 35050902, 2022). "The data on the immune, stromal, and ESTIMATE scores and tumor purity were generally consistent with previous results, indicating that the high abundance of SPINK1 suggests a “hot” state of accumulation of highly infiltrating immune cells, termed a “better” immune score." (PMID 35924241, 2022). "Specifically, the overexpression of SPINK1 in the samples suggested the possibility of a hot tumor, in which effector T cells may play the central part in the antitumor response; therefore, patients with a hot TIME are more likely to respond to immunotherapy." (PMID 35924241, 2022). "Furthermore, it is interesting that, similar to the in vitro ALL cell transendothelial migration experiment, high-dose SPINK1 seems to promote tumor cell infiltration in the brain tissue of ALL model mice." (PMID 35194087, 2022). "SPINK1, as a trypsin inhibitor, might also be involved in progression of invasion through tumor-extracellular matrix interaction." (PMID 36053457, 2022). "As expected, ERG and SPINK1 overexpression were mutually exclusive at each tumor focus." (PMID 35050902, 2022). "Lastly, other IHC biomarkers previously used in assessing PCa heterogeneity, such as PTEN and SPINK1, could potentially be employed in future studies to even better discriminate tumor populations on pathology review." (PMID 35220606, 2022). "Thirdly, the preliminary data derived from the GO and KEGG analyses deciphered in part why SPINK1 could be a potential biomarker for the prediction of an immunologically hot tumor, which is possibly suitable for subsequent ICB therapy response in HCC." (PMID 35924241, 2022). "As such, in vivo assay confirms that circRPS16 knockdown inhibits SPINK1 and tumor growth." (PMID 34595116, 2021). "Furthermore, immunocytochemistry (ICC) of the PSCA, CD36, and SPINK1 proteins confirms their colocalization in the BrdU-labeled cSCs within the tumor spheroids." (PMID 34360875, 2021). "Whether SPINK1 protein levels are above detectable levels in plasma of cancer patients is another important issue to exploit it as a biomarker of the hypoxic tumor burden." (PMID 34747365, 2021). "Importantly, silencing circRPS16 inhibited tumor growth by downregulating SPINK1 expression in vivo." (PMID 34595116, 2021). "Eventually, our results show that circRPS16 inhibits tumor growth via SPINK1 in vivo." (PMID 34595116, 2021). "All of these data demonstrate that SPINK1 in plasma reflected the degree of hypoxia within tumor tissue in vivo and that SPINK1 could have been a good plasma marker for tumor hypoxia." (PMID 34747365, 2021). "Additionally, in vivo assays demonstrated that circRPS16 knockdown inhibited tumor growth by inhibiting SPINK1 expression." (PMID 34595116, 2021).
tumor (continued). "The aberrant activation of SPINK1 signaling could contribute to tumor malignancy, including increased invasion and proliferation of tumor cells." (PMID 32326089, 2020). "More recently, SPINK1 has also been found to be expressed by the tumor stroma after chemotherapy, where it may contribute to chemoresistance and increased risk of recurrence." (PMID 30778387, 2019). "Efforts to identify the SPINK1 target(s) and signaling pathways of interest could lead to identification of new biomarkers and novel points of intervention to reduce tumor cell survival and prevent spread of metastatic disease." (PMID 30778387, 2019). "Also, stable overexpression of these microRNAs in SPINK1‐positive PCa cells exhibit reduced tumor growth and distant metastases in murine xenograft model." (PMID 29460395, 2018). "Moreover, ectopic expression of miR‐338‐5p and miR‐421 abrogates SPINK1‐mediated oncogenesis, tumor growth and distant metastases in murine xenograft model." (PMID 29460395, 2018). "Next, we asked whether therapeutically eliminating SPINK1 from the full SASP spectrum of damaged stoma would further enhance the therapeutic response of tumours." (PMID 30333494, 2018). "Together, these results suggest that combining a SPINK1-targeting agent with conventional chemotherapy has the competence to enhance tumour response without causing severe cytotoxicity." (PMID 30333494, 2018). "Moreover, monoclonal antibodies to either SPINK1 or EGFR (cetuximab) significantly slowed down tumor growth in SPINK1‐positive tumor xenografted mice." (PMID 25809148, 2015). "SPINK1 is a secreted protein and is therefore a candidate circulating tumour marker." (PMID 23527199, 2013). "Clinical and histopathological data in 86 patients with HCC according to tumour cell SPINK1 status." (PMID 23527199, 2013). "Finally, the evaluation of ERG, TFF3, and SPINK1 could be an attractive approach to determine both tumor heterogeneity and PCa subtypes." (PMID 38256434, 2024). "Although our present study focuses on SPINK1-mediated tumor plasticity as one potential mechanism contributing to the functional enrichment of CD133+ cells following chemotherapy, other mechanisms, including survival signaling pathways and the TME, may also play significant roles." (PMID 38030644, 2023). "Thus, we hypothesized that SPINK1 may possibly exert its carcinogenic effects on tumor cell’s survival at least in part via autophagy signaling and regulation." (PMID 37305325, 2022). "Moreover, IHC staining using clinical RCC tissues demonstrated that, whereas HIF-1α was expressed in entire tumor tissue including the proximal regions of tumor vessels due to the loss of VHL, SPINK1 expression was predominantly detected in perinecrotic regions distal to blood vessels." (PMID 34747365, 2021). "Patients with tumors expressing SPINK1 face a poorer overall prognosis and stimulation of SPINK1 expression in the treatment-damaged tumor microenvironment may further contribute to chemoresistance and tumor recurrence." (PMID 30778387, 2019). "Importantly, SPINK1 silencing mediated upregulation of various Metallothionein isoforms, considered as tumor suppressors in CRC, confer sensitivity to doxorubicin, which strengthens the rationale for using the combinatorial treatment approach for the SPINK1-positive CRC patients." (PMID 26258891, 2015). "However, in CRC initiation whether upregulation of SPINK1 takes place first or downregulation of MTs, which one is the important step for triggering tumor initiation and later progression is an important question that remains to be elucidated." (PMID 26258891, 2015). "Correlation analysis in both human HCC tumor samples and in the NRasV12+Myr-AKT proto-oncogenes-driven HCC tumor mouse model likewise found ELF3/Elf3 and SPINK1/Spink1 expression to positively correlate." (PMID 38030644, 2023).
tumor (continued). "Lentivirus-mediated suppression of SPINK1 reduces stemness and induces a more differentiated HCC tumor; while combination therapy with 5-FU leads to a more maximal suppression, driving the HCC cells toward a more differentiated lineage." (PMID 38030644, 2023). "When considering all tumor foci, the frequency of ERG (59.5%, P = 5.8 × 10–5) and SPINK1 (22.6%, P = 8.9 × 10–5) overexpression was significantly higher than when considering the index focus alone." (PMID 35050902, 2022). "Unexpectedly, a high level of SPINK1 expression was found to be significantly and positively correlated with the high expressions of PD-1, LAG-3, TIM-3, TIGIT, and CTLA-4 in the tumor samples from the TCGA cohort." (PMID 35924241, 2022). "In the training dataset, we found that the ROC curves plotted for SPINK1 separated the stage I and II HCC samples from the normal adjacent to tumor controls with high discriminatory accuracy." (PMID 35924241, 2022). "Of the 251 prostatectomy specimens harboring multiple tumor foci, ERG/SPINK1 IHC was performed on all foci in 233 (92.8%) specimens to be able to evaluate for interfocal heterogeneity." (PMID 35050902, 2022). "Freshly isolated cells were additionally characterized for specific mRNA expression of tumor (GPC3, SPINK1, SPP1, KPNA2) and fibroblast (COL1A2, TWIST2, FGF7) marker genes using RT–qPCR." (PMID 36077764, 2022). "Our data clearly showed that the high abundance of SPINK1 corresponded with the high levels of CD4+ and CD8+ effector T lymphocytes, as well as activated dendritic and natural killer cells in the same tumor samples." (PMID 35924241, 2022). "Then RNA was extracted from tumor tissue, and qRT-PCR showed that the expression of NEAT1, IL-34, VEGFA, SPINK1, S100A14, and P4HA2 was downregulated and the expression of CCNE2 was upregulated in NEAT1 knockdown tumor tissue." (PMID 36213831, 2022). "The SPINK1 and SPINK1+AFP models exhibited a higher discriminatory efficacy than did AFP alone in stage I and II tumor samples: AUC = 0.72:0.72:0.53, specificity = 92.0%:92.4%:90.6%, sensitivity = 46.9%:45.7%:23.4%." (PMID 35924241, 2022). "For further characterization of PHCs, the expression of the following HCC-specific tumor markers was investigated: GPC3, SPINK1, SPP1 and KPNA2." (PMID 36077764, 2022). "SPINK1, FABP4, and MMP10 showed darker staining in tumor tissues, and GPRASP1, CLCA4, and LAMP5 showed lighter staining." (PMID 35479956, 2022). "The SPINK1 general cancer pathway and HGF signalling were activated in G3 cells in which the tumour malignancy‐related genes RASD1, PIK3R1, JUN, and FOS were significantly upregulated, indicating that G3 promotes malignant progression in GC." (PMID 35184420, 2022). "The downregulated gene GIMAP1, with a hazard ratio (HR) < 1, was regarded as a tumor suppressor, while the upregulated genes ANO1, DSG3, and SPINK1, with a HR > 1, were considered oncogenes." (PMID 33901011, 2021). "Treatment with cetuximab or bevacizumab combined with SPINK1, a PRSS inhibitor, reduced tumor growth efficiently compared with cetuximab or bevacizumab alone in xenograft models." (PMID 33916984, 2021). "Next, we compared the mRNA levels of SPINK1 with those of one of the most representative intrinsic hypoxia markers, CA9, in 36 subcutaneous HeLa tumor xenografts by qPCR." (PMID 34747365, 2021). "The mRNA expression of SPINK1, DSG3, ANO1 were significantly increased in PAAD tumor tissue while GIMAP1 were significantly decreased compared with normal tissues." (PMID 33901011, 2021). "Of note, when either cetuximab or SPINK1 mAb was co-administered with MIT as dual agents, tumour showed further reduction (34.6% and 46.3%, respectively)." (PMID 30333494, 2018). "Tumor subtypes for the 49 tumor samples were assigned based on the DASL expression data of ERG, ETS, and SPINK1." (PMID 28027300, 2016).
tumor (continued). "To investigate the tumorigenic potential of SPINK1 in CRC progression, we employed the chick embryo chorioallantoic membrane (CAM) model for tumor growth, to assess cell intravasation and metastases to distant organs." (PMID 26258891, 2015). "SPINK1-positive tumour cells were seen in 67 of the 86 (79%) HCC cases; the frequency of positive tumour cells ranged from occasional, dispersed cells to present in all tumour cells." (PMID 23527199, 2013). "SPINK1 can activate the EGF receptor and treatment of tumour xenograft-bearing mice with antibodies to SPINK1 or EGR receptor reduced tumour growth, suggesting SPINK is a potential therapeutic target." (PMID 23527199, 2013). "Furthermore, genome-wide studies show that SPINK1 expression has a considerable predictive value in HNSCC, supporting its potential as a tumor biomarker." (PMID 40872585, 2025). "Intriguingly, the expression of SPINK1 in tumor nodules is not homogeneous, suggesting cellular heterogeneity of SPINK1 expression levels." (PMID 38540686, 2024). "The oncogene-enriched type mainly involves upregulated genes related to tumor cell proliferation and invasion, including Claudin3 (CLDN3), Claudin4, serine peptidase inhibitor Kazal type 1 (SPINK1), epithelial splicing regulatory protein 1 (ESRP1), and epithelial cell adhesion molecule (EpCAM)." (PMID 38611084, 2024). "A total of 103 samples from 20 PCa patients were analyzed; foci of adjacent non‐tumor prostate tissue, HGPIN, GL3, GL4, GL5, and LN were examined to determine the presence of the TMPRSS2‐ERG fusion and ERG, EZH2, NKX3.1, and SPINK‐1 expression levels, using RT‐PCR." (PMID 36199157, 2023). "Multiplex staining also confirmed co-localization of SPINK1 and ELF3 in human HCC tumor samples." (PMID 38030644, 2023). "It will be interesting to also further explore how the suppression of SPINK1 affects the tumor microenvironment (TME), including immune cells; as well as what other cell types in the niche may secrete SPINK1 to promote HCC." (PMID 38030644, 2023). "Indeed, co-immunoprecipitation (Co-IP) of SPINK1 and EGFR in HCC cells confirmed their binding; while multiplex immunostaining demonstrated their colocalization in human HCC tumor samples." (PMID 38030644, 2023). "Upon 5-FU and cisplatin treatment, ELF3-mediated transcription and secretion of SPINK1 increase, and potentiate HCC cells’ ability to promote tumor initiation, stemness, dedifferentiation and chemoresistance, by binding to EGFR and consequently driving the ERK-CDK4/6-E2F2 signaling cascade." (PMID 38030644, 2023). "Immunoreactivity of post-SPINK1 significantly differed by tumor stage (p = 0.040), lymph node stage (p = 0.019), metastasis status (p = 0.026) and disease stage (p = 0.036)." (PMID 36053457, 2022). "Secreted SPINK1 proteins enhanced radioresistance of cancer cells even under normoxic conditions in EGFR-dependent and nuclear factor erythroid 2–related factor 2–dependent (Nrf2-dependent) manners and accelerated tumor growth after radiotherapy." (PMID 34747365, 2021). "SPINK1 proteins were also observed in the tumor tissue, but it is noteworthy that SPINK1 protein did not exhibit a homogeneous expression pattern; a strong signal was predominantly detected in perinecrotic regions distal to blood vessels." (PMID 34747365, 2021). "In contrast to placebo, MIT administration generated remarkably decreased tumour sizes regardless of the presence of SPINK1 in stromal cells, validating the efficacy of MIT as a cytotoxic agent." (PMID 30333494, 2018). "Another potential limitation is that molecular subtyping was done using tissue microarray samples of the index tumor, which may lead to errors in prevalence estimates for alterations that are heterogeneous, such as PTEN and SPINK1." (PMID 28186998, 2017).